BRCA1 (BRCA1 DNA repair associated)
Diseases named in the same sentence as BRCA1 in open-access papers (continued):
Sharing a sentence is not in itself a finding about the gene and the disease.
breast cancer (continued). "Women with BRCA1 mutations who breastfed for more than one year were found to have a 22–50% reduced risk of breast cancer than those who never breastfed." (PMID 36164270, 2023). "Nonetheless, the rate of non-BRCA pathogenic variations was higher than those of BRCA1 or BRCA2 pathogenic variations especially in bilateral breast cancer patients." (PMID 36896237, 2023). "Inflammasome inhibitor, glibenclamide, treatment ameliorates Brca1 mutant breast cancer metastasis." (PMID 36932407, 2023). "In exploratory analyses in BRCA1 or BRCA2 mutation carriers, there was little evidence of association of E354Q with breast cancer risk (BRCA1:OR 1.00, 95% CI:0.96–1.05, p = 0.98; BRCA2:OR:1.04, 95% CI:0.98–1.11, p = 0.16)." (PMID 37250804, 2023). "The addition of n-3 PUFAs has been reported to increase Brca1 expression in rat mammary tumors." (PMID 37120599, 2023). "Finally, tumors categorized as Triple-Negative BC (TNBC), which are negative for HER2, ER, and PgR, are usually associated with mutations in the breast cancer 1 (BRCA1) gene and represent the most aggressive and invasive BC type, with a mean of survival rate of 13 to 18 months after diagnosis." (PMID 36986040, 2023). "In the prospective analysis of BRCA1 pathogenic variant carriers, we found that higher baseline BMI and adult weight gain were associated with higher risk of postmenopausal breast cancer, but not with risk of premenopausal breast cancer." (PMID 37340476, 2023). "Moreover, next-generation sequencing revealed that beyond BRCA1/2, mutations in homologous recombination effectors, such as PALB2, RAD51, ATM, BRIP1, BARD1, and CHEK2 also occur in breast cancer." (PMID 36613148, 2023). "Our data showed a protective effect of high PAF-AH expression in BRCA1 mutant breast cancer." (PMID 36614323, 2023). "In the group of patients with breast cancer diagnosed at age below 51 and above 50, the results of BRCA1/2, NOD2, CDKN2A, NBN, PALB2 and RECQL mutation were not statistically significant." (PMID 37434214, 2023). "Therefore, the primary aim of this study was to investigate the effect of RRSO in a large cohort of female BRCA1/2 GPV carriers on breast cancer incidence and its histopathological features." (PMID 37046756, 2023). "RRSO did not decrease breast cancer risk overall (HR: 1.23, 95% CI: 0.85–1.78), or for BRCA1 (HR 1.29: 95% CI: 0.81–2.05) or BRCA2 GPV separately (HR: 1.13, 95% CI: 0.62–2.06)." (PMID 37046756, 2023). "In particular, Ru(η6-arene)(PTA)Cl2 (PTA = 1,3,5-triaza-7-phosphaadamantane), or RAPTA, complexes have demonstrated efficacy against breast cancer by suppressing metastasis, tumorigenicity, and inhibiting the replication of the human tumor suppressor gene BRCA1." (PMID 37552495, 2023). "An example can be seen in hereditary breast cancer whereby the demand for genetic testing to predict hereditary risks is increasing since the discovery of BRCA1 and BRCA2 genes as breast cancer susceptibility genes, which account for 5%–10% of hereditary breast cancer cases." (PMID 37168509, 2023). "Based on our results, in Poland, we use a panel of founder mutations in BRCA1, BRCA2, CHEK2, and PALB2 as an initial screening tool for all patients with breast cancer and unaffected individuals with a positive family history of breast cancer." (PMID 37510234, 2023). "Interestingly, it has been reported in breast cancer that BRCA1 promoter methylation is correlated strongly and specifically with both BRCA1 gene expression in ER − tumors and KRT7 promoter methylation with KRT7 gene expression in ER + tumors." (PMID 37369946, 2023).
breast cancer (continued). "There was a suggestion for increased premenopausal breast cancer risk for taller BRCA1 and BRCA2 variant carriers, but the association was not significant (HR 1.19 per 10 cm increase, 95% CI 0.91–1.56 and HR 1.32, 95% CI 0.92–1.90, respectively)." (PMID 37340476, 2023). "Thus, in addition to BRCA1 and BRCA2, many other genes have been identified as susceptibility genes for breast cancer." (PMID 36896237, 2023). "When stratified by gene group, 2,721 (3.5%) individuals had BRCA1/2 PLPV on comprehensive sequencing of BRCA1/2; 3,489 (4.5%) individuals had a PLPV in one of the seven high-risk breast cancer genes; and 5,944 (7.7%) had a PLPV in one of the 19 breast or ovarian cancer genes." (PMID 37535880, 2023). "We found that ZNF251 knockdown caused olaparib resistance in BRCA1-mutated but not BRCA1-wildtype breast cancer cells." (PMID 37066268, 2023). "Because BRCA1 is specifically associated with the triple‐negative phenotype of breast cancer disease, we expected to increase the number of BRCA1 heterozygotes." (PMID 36000185, 2023). "History has shown that an increase in mutated BRCA1 or BRCA2 can put patients at higher risk of developing cancer, but the origin of many of these breast cancer cell lines studied may have mutated." (PMID 38137912, 2023). "In contrast with these data, a large retrospective study from the Breast Cancer Linkage Consortium documented an increased risk of EC in BRCA1-mutated women but not in BRCA2-mutated women." (PMID 36837501, 2023). "Whole-exome sequencing data from 98 BRCA1/BRCA2/PALB2 founder mutation-negative Northern Finnish breast cancer cases with indications of hereditary disease susceptibility was used for the identification of rare CNVs." (PMID 37578974, 2023). "Similarly, the PARPi olaparib has been combined with the α-selective PI3K inhibitor alpelisib in a Phase 1b study of recurrent triple-negative or germline BRCA1 and BRCA2-mutated breast cancer." (PMID 37430137, 2023). "The combined results from the two studies strongly indicate a low frequency of BRCAness among non-BRCA1/BRCA2 familial breast cancer patients with no identified variants in other HRD genes." (PMID 37316882, 2023). "These interconnected events may culminate in the development of hormone-dependent tumor formations, further emphasizing the complex interplay of BRCA1 in the context of breast cancer etiology." (PMID 37762577, 2023). "To address these questions, we analyzed BRCA1 methylation status in breast cancer tissue and matched white blood cells (WBC) from 408 patients with 411 primary breast cancers, including 66 TNBCs, applying a highly sensitive sequencing assay, allowing allele-resolved methylation assessment." (PMID 38053165, 2023). "Mutations in BRCA1 and BRCA2 possess a higher risk of developing breast cancer in women." (PMID 36631481, 2023). "Notably, heterozygous mutations in FA genes, such as BRCA1/FANCS and BRCA2/FANCD1, increase the risk of cancer development, particularly in breast cancer." (PMID 37958890, 2023). "We also demonstrated that GATA3 functions downstream of BRCA1 to suppress EMT in breast cancer." (PMID 37353480, 2023). "Patients with breast cancer carrying BRCA1 and BRCA2 genetic alterations show poor prognoses." (PMID 36865806, 2023). "Two different potential roles have been described for MSCs in the development of triple-negative breast cancer (TNBC) with BRCA1 gene mutation (aka IRIS, for In-frame Reading of BRCA1 Intron 11 Splice variant), which is the most aggressive breast cancer subtype." (PMID 36830980, 2023). "BRCA1 and BRCA2 mutations represent the most well-known mutations in breast cancer." (PMID 38068930, 2023). "BRCA1 and BRCA2 mutation carriers represent 5–10% of females with breast cancer." (PMID 37987348, 2023). "Unraveling BRCA1’s role in cellular differentiation has the potential to reveal new insights into breast cancer development and may pave the way for innovative treatment strategies." (PMID 37762577, 2023).
breast cancer (continued). "The combination of these HR defects was hypothesised to result in chemoresistance and, thus, the poorer outcomes in patients with BRCA1-altered breast cancer, and may show a similar correlation in familial breast cancers." (PMID 36831687, 2023). "In this large cohort of women carrying a pathogenic variant in BRCA1 or BRCA2, we found associations of height, BMI, and weight gain with breast cancer risk in pre- and postmenopausal women, which were generally consistent in direction and magnitude with those described in the general population." (PMID 37340476, 2023). "Currently, only BRCA1/2 testing (not more comprehensive breast cancer MGPTs) is recommended for use in high-risk women by the USPSTF." (PMID 37435610, 2023). "To observe potential genetic interactions between BRCA1/2 and ALDH2 in a real‐world setting, we set out to recruit cases of BRCA1 and BRCA2 mutation carriers from breast cancer centers in Japan, and we determined ALDH2 genotypes using the previously established Taqman PCR assay." (PMID 36345163, 2023). "Since the identification of BRCA1 and BRCA2 thirty years ago, many other genes have been proposed to be associated with moderate to high risk for breast cancer; however, limited and sometimes contradictory findings from studies have impeded a conclusive annotation." (PMID 37444426, 2023). "No individual BRCA1 variants were significantly associated with cancer or breast cancer specifically within this sample, most likely due to sample size." (PMID 37306523, 2023). "Unlike other cancers with specific mutations such as BRCA1/2 in breast cancer and EGFR in lung cancer, ESCC lacks tumor-specific mutations." (PMID 37553345, 2023). "Together, these results show that the downregulation of BRCA1 by miRNA-182 stops DNA repair and may affect how breast cancer is treated." (PMID 37808196, 2023). "A similar pattern (with an association for BRCA1- but not BRCA2-associated breast cancer) has been observed for oral contraceptive use." (PMID 37340476, 2023). "Notably, the study highlighted how hypoxia hampers the differentiation induced by HDAC inhibitors in BRCA1-reconstituted breast cancer cells." (PMID 37762577, 2023). "In order to perform multi-scale characterisation and explore the heterogeneity of HRD, we present a mutational signature-based classifier of HRD for exome-sequenced breast cancers which we then apply to develop a transcriptional signature of HRD and BRCA1/2 deficiency." (PMID 37919776, 2023). "Furthermore, it regulates BRCA1 expression in breast cancer cells and ultimately inhibits tumor growth." (PMID 37724907, 2023). "Subsequently, the NEOTALA study tested talazoparib monotherapy preoperatively in BRCA1/2 mutated HER2 negative breast cancers showing pCR rates of 49%, which is numerically comparable to those receiving neoadjuvant chemotherapy." (PMID 37569851, 2023). "Notably, we observed strong downregulation of BRCA1 (z = −3.5), indicating the potential generation of a functional ‘BRCAness’ phenotype upon SOC treatment in the BRCA1/2-wt ER+ MCF-7 breast cancer cells." (PMID 37914699, 2023). "The MEDIOLA open-label, Phase I/II trial tested the safety and activity of olaparib plus durvalumab in patients with germline and non-germline mutated BRCA1/2 metastatic breast cancers." (PMID 37035242, 2023). "Among these genes, Breast Cancer 1 (BRCA1) and Breast Cancer 2 (BRCA2) have been reported to have variations that increase the risk of developing breast and ovarian cancers by more than 60% basically suggesting these variations as one of the leading causes of breast and ovarian cancers." (PMID 36896237, 2023). "In conclusion, our study reported a cohort of Taiwanese breast cancers harboring mutations in BRCA1, BRCA2, and PALB2 through tumor-only sequencing, which underscores the impact of BRCA1/2 and PALB2 on breast cancer risk and potential therapeutic opportunities." (PMID 38098088, 2023).
breast cancer (continued). "Furthermore, evidence has been presented that H19 depletion increases sensitivity to PARP inhibitors via ILF2 in ER+ breast cancer cells with wild-type BRCA1 and in BRCA1 mutant triple-negative breast cancer cells." (PMID 37298108, 2023). "Evidence suggests that the increased plasma and blood cells miR-155-5p is an immunologic response during the early stages of breast cancer, which might imply a BRCA1-independent response." (PMID 37240365, 2023). "Women who carry the mutations of BRCA1 and BRCA2 have a higher risk of developing breast cancer." (PMID 37623253, 2023). "BRCA mutations: For women with BRCA1 (n=685) mutations, breastfeeding for more than one year was associated with a 22-50% reduced risk of breast cancer compared to those women who never breastfed (OR=0.55, 95% CI=0.38 to 0.80; P=0.001)." (PMID 37750138, 2023). "To summarize, consensus on the effect of RRSO on breast cancer risk in BRCA1/2 GPV has not yet been reached." (PMID 37046756, 2023). "In addition, a shift of BRCA1 protein expression from exclusively nuclear to both nuclear and cytoplasmic is characteristic of canine mammary tumors, especially of the malignant type." (PMID 37835752, 2023). "Moreover, BRCA1- and BRCA2-defective breast cancer cells, display an increased somatic mutational load specific of TLS polymerases." (PMID 36749784, 2023). "Our findings suggest that BRCA1 c.5309G>T and BRCA2 c.1310_1313delAAGA mutations may have a strong founder and/or recurrent effect on breast cancer among the Northeastern Moroccan population." (PMID 37055759, 2023). "Furthermore, in vivo study in 4T1 induced breast cancer mouse model showed that the tumor growth rate and final volume were decreased significantly in the mouse group treated intravenously with BRCA1 + NPs and BRCA2 + NPs formulations." (PMID 36631481, 2023). "Of two studies on BRCA1/2, one showed no variants in 24 cats with mammary carcinoma, while the other identified four germline variants of BRCA1 (intron 9) in three out of the nine FMC-bearing cats genotyped." (PMID 37626804, 2023). "Although the overall rate was low, the comparable rates of detection between BRCA1/2 and non-BRCA1/2 variants implies that extended testing may be particularly beneficial in women with LBC and a family history of breast cancer." (PMID 33763779, 2022). "We report for the first time the existence of BRCA1 SNPs in Ghanaian females with breast cancer." (PMID 36942145, 2022). "TBX2 may be involved in malignant progression as its overexpression correlates with advanced tumor stages and with aggressive, hereditary BRCA1/2 breast cancers." (PMID 35846378, 2022). "In this vein, BRCA1/2 is directly connected to breast cancer and the notion of masculinity, according to which only women have breast tissue, may prevent men from looking for information and help." (PMID 35448177, 2022). "Genetic characteristics of the study population: BRCA1 or BRCA2 mutations may be responsible for approximately 10% of ovarian cancer cases and 3–5% of breast cancer cases." (PMID 35950060, 2022). "This process may delay the decision for simultaneous RRSO or contralateral prophylactic mastectomy with cancer surgery in BRCA1/2 gene PV or LPV carriers with breast cancer." (PMID 35115620, 2022). "There are miRNAs that regulate BRCA1 expression in triple-negative sporadic breast cancer cases." (PMID 35740092, 2022). "However, it is very likely that BRCA1/2 testing among those with breast cancer was covered during this time period by private insurers, and personal communication with Massachusetts Medicaid officials confirmed that it was covered by Massachusetts Medicaid." (PMID 35312162, 2022). "The BRCA1 c.798_799detTT frameshift variant is cited twice in the Breast Cancer Information Core (BIC) database, without any ethnic origin indicated." (PMID 35216584, 2022).
breast cancer (continued). "In addition to breast cancer, BRCA1 was identified as a transcriptional repressor of the IGF1R gene in prostate and endometrial cancer cells." (PMID 35432218, 2022). "For this purpose, we used as study models the breast cancer-derived cell line HCC1395, which carries the pathogenic nonsense variant R1751X in homozygosis, and a set of HeLa cells stably expressing BRCA1 C-terminal constructs carrying selected nonsense variants." (PMID 35837282, 2022). "The benefit of talazoparib in BRCA1/2-mutated patients with human epidermal receptor-2 (HER2) negative advanced breast cancer (ABC) has been demonstrated in several phase I/II clinical trials." (PMID 36045677, 2022). "This is further reflected by several preclinical studies showing that BRCA2-mutated, but not BRCA1-mutated breast cancers, are responsive to treatment with ICIs." (PMID 36077694, 2022). "Breast cancers harboring germline mutations in either BRCA1 or BRCA2 are highly sensitive to PARP inhibitors, and thus, inhibiting PARPs has become a therapeutic strategy for targeting BRCA1/2-mutated cancer cells." (PMID 36209184, 2022). "BRCA1 is downregulated in many sporadic cases of breast cancer." (PMID 36193432, 2022). "In 34% of the breast cancer cases, the promoter region of BRCA1 was hypermethylated." (PMID 35740092, 2022). "To investigate the cytotoxic effect of combined EZH2 and ATM inhibition in human BRCA1-mutant breast cancer, we treated the human TNBC cell lines SUM149 (BRCA1-mutant) and CAL120 (BRCA1-wild type) with GSK126 and AZD1390, and analyzed cell viability using CellTiter-Glo and clonogenic survival." (PMID 35715861, 2022). "Overall, our results suggest that women with breast cancer who have BRCA1/2 mutations are not at increased risk of anthracycline-induced cardiotoxicity relative to those with sporadic breast cancer." (PMID 35242827, 2022). "Our findings do not support a role for increased cardiotoxicity risk with BRCA1/2 mutations in women with breast cancer." (PMID 35242827, 2022). "We individually examined the genetic alterations of BRCA1/2 in breast cancer using cBioPortal." (PMID 35409110, 2022). "In a single-center, cross-sectional study, we investigated differences in cardiac function and cardiopulmonary fitness through comprehensive phenotyping of breast cancer survivors with and without BRCA1/2 mutations." (PMID 35242827, 2022). "Notably, the transcription factor, SOX11, a progenitor cell and lineage regulator of non-mammary cell types, is found to be highly expressed in some Brca1−/− mammary tumors." (PMID 35846378, 2022). "BRCA1 and TGFβR2 expression levels are inversely related in human breast cancers." (PMID 35236825, 2022). "The prognostic importance of BRCA1/2 in breast cancer was investigated in this research." (PMID 35409110, 2022). "BRCA1 and BRCA2 mutations account for approximately 5% of all breast cancer cases." (PMID 35743744, 2022). "Thus, the results obtained in the course of this research allowed us to formulate a number of definitions and new provisions for the possibility of using BRCA1 gene parameters for a personalized approach to the treatment of breast cancer." (PMID 36613648, 2022). "In particular, we discovered a new gene signature to identify breast cancer tumors that are likely to respond to cisplatin in the absence of BRCA1 mutations." (PMID 35626009, 2022). "BRCA1 mutations associated with breast cancers are usually basal-like and triple-negative without HER2 gene amplification." (PMID 35300046, 2022).